CTBP2P3 (CTBP2 pseudogene 3)
Gene: Processed pseudogene on chromosome 18 (60,663,115 to 60,664,369, forward strand). Ensembl gene ENSG00000267153.
Diseases named in the same sentence as CTBP2P3 in open-access papers:
CTBP2P3 is named in the same sentence as 1 disease in open-access papers, as found by Europe PMC text mining. Sharing a sentence is not in itself a finding about the gene and the disease.
CTBP2P3 shares sentences with these, for which no sentence is quoted: depression (1 paper).